EZH2 (enhancer of zeste 2 polycomb repressive complex 2 subunit)
Diseases named in the same sentence as EZH2 in open-access papers (continued):
Sharing a sentence is not in itself a finding about the gene and the disease.
cancer (continued). "Consistently, both genetic or pharmacologic inhibition of EZH2 enhanced H-2Kb and β2M expression and reduced H3K27me3 modification levels on H2K1 and B2m promoter region in RM1 and MC38 cancer cells." (PMID 41252204, 2025). "Moreover, the expression of EZH2 and HOTAIR have been found to be regulated by estradiol or environmental endocrine disrupting chemicals in several cancers and in vitro." (PMID 40868070, 2025). "Similarly, in cancer, ZDHHC5's role in palmitoylating oncogenic proteins like EZH2 and PD-1 suggests its potential as a therapeutic target." (PMID 40180214, 2025). "The phenomenon that EZH2 has been observed to be overexpressed in various types of cancers but not in normal tissues attracts people's attention." (PMID 40028035, 2025). "The potential of EZH2 inhibitors in overcoming cisplatin resistance and promoting subtype switching in SCLC presents a promising therapeutic avenue, offering a novel strategy for managing this aggressive cancer." (PMID 41220942, 2025). "Furthermore, investigations have revealed the potential synergy between TIC10 and EMs such as EZH2 inhibitors and HDAC inhibitors across multiple cancer types, substantiating the rationale for such combination strategies." (PMID 40673385, 2025). "EZH2 also has a PRC2- and H3K27me3-independent role in cancer." (PMID 39636550, 2025). "Enhancer of Zeste Homolog 2 (EZH2), a central component of the Polycomb Repressive Complex 2 (PRC2), possesses histone methyltransferase activity through its SET domain and is frequently overexpressed in various cancers." (PMID 41209556, 2025). "Additionally, previous studies have identified a dual upregulation of EZH2 and TOP2A during cancer progression." (PMID 40271060, 2025). "EZH2 can physically interact with signal transducer and activator of transcription 3 (STAT3) and methylate STAT3 directly, promoting nuclear retention and increasing the activity of STAT3 and therefore exacerbating cancer." (PMID 40028035, 2025). "Therefore, effectively triggering the degradation of both the EZH2 oncoprotein and its MYC partner represents an attractive therapeutic strategy for cancer." (PMID 39823459, 2025). "EZH2 is a core member of the PRC2 protein family and a functional enzyme component of PRC2, EZH2 acts as a histone methyltransferase that influences the development of a variety of cancers." (PMID 39850359, 2025). "In addition, EZH2 can likewise take part in various molecular signaling pathways, like PI3K/Akt/mTOR and JAK2/STAT3, to promote the proliferation and migration of cancer cells." (PMID 41154714, 2025). "We found correlations between activity of the histone methyltransferase PRC2 and sensitivity to cPLA2α inhibition, and cPLA2α inhibitors showed similar anti-cancer activity to inhibitors of the catalytic component of PRC2, EZH2, suggesting overlapping mechanisms of action." (PMID 39747052, 2025). "The high proliferation index of EZH2 in tumors is usually related to the overexpression of EZH2.The absence of EZH2 can inhibit the growth of cancer cells, induce senescence and apoptosis, and reduce invasion and metastasis." (PMID 40535805, 2025). "Similarly, lysine methyltransferases, including EZH2, DOT1L, G9A, and SUV39H1, catalyze Kme, and are also the clinical drug targets for cancer treatment." (PMID 38862432, 2024). "EZH2 may bind to and methylate STAT3, which leads to enhanced STAT3 activity by increased tyrosine STAT3 phosphorylation, suggesting its key role in cancer." (PMID 39204206, 2024). "A specific EZH2 inhibitor, Tazemetostat or EPZ-6438 (35-fold stronger inhibition of EZH2 than EZH1, and ~100 fold stronger than other methyltransferases) is an FDA-approved drug used in cancer therapy." (PMID 39703699, 2024).
cancer (continued). "First and foremost, while the pivotal role of EZH2/PRC2 in promoting and counteracting cancer in HNSCC has been extensively investigated, further elucidation is needed regarding the regulation of its diverse expression mechanisms in HNSCC patients across different clinical scenarios." (PMID 38600608, 2024). "Studies in acute viral models have demonstrated that the absence of EZH2 leads to an elevated expression of memory-related transcripts like TCF-7, which is associated with the stem-like CD8+ T cells observed in cancer." (PMID 38534385, 2024). "Recently, compounds that disrupt the interaction between EZH2 and EED have been developed, leading to the destabilisation and degradation of PRC2 proteins, which could provide a new avenue for cancer therapy." (PMID 39236081, 2024). "Likewise, histone methyltransferase EZH2 and histone H3K36 trimethyltransferase SETD2 have been reported as vital epigenetic factors regulating neutrophil infiltration during cancer metastasis." (PMID 39133578, 2024). "Compounds targeting these pathways may be active based on preclinical mechanistic cancer models and/or based on cancer patient data, including immune checkpoint blockade (anti-PD-1/PD-L1) and inhibitors of mTOR, PARP, ATR, EZH2, and HDAC." (PMID 39697230, 2024). "Moreover, one of the most important mechanisms leading to cancer immune evasion, namely the suppression of the MHC-class I antigen processing pathway, can be induced by EZH2, favoring an immunosuppressive microenvironment." (PMID 39769907, 2024). "Our results highlight the essential role of HOTAIR in pan-cancer and uridine bypass, suggesting that the HOTAIR/EZH2/UPP1 axis might be a novel target for overcoming CRC." (PMID 38696320, 2024). "EZH2 suppresses ferroptosis in HCC by downregulating TFR2, and combining EZH2 inhibitor tazemetostat with sorafenib enhances sorafenib sensitivity and anti-cancer effects." (PMID 39315094, 2024). "ALK expression was associated with methylation of regions/probes harboring repressive histone marks as indicated by the enrichment of chromatin regulators of the PRC2 complex (EZH2, SUZ12, and JARID2), which has been described as “epigenetic switching” in cancer." (PMID 38585847, 2024). "The enzymatic subunit of polycomb repressive complex 2 (PRC2), EZH2, a histone-lysine N-methyltransferase responsible for transcriptional silencing, is increased in CTH, CTO, CTP, and CEGBCs cells, as reported in several cancers of poor prognosis." (PMID 38893091, 2024). "Moreover, an inverse correlation between EZH2 and RUNX3 expression has been shown to be dependent on the trimethylation of histone H3K27 on RUNX3 gene promoter, in several cancer cell lines." (PMID 39769907, 2024). "EZH2 inhibition also upregulated the protein expression of FOXP2 in human cancer lines H460, H2030, A549, and BEAS-KP, but not in immortalized epithelial cell lines HBEC3KT and BEAS2B." (PMID 36670102, 2023). "In view of the functional role of EZH2 and PTMA in cancer the ceRNA regulatory network targeting these two genes may be investigated in GBC." (PMID 36873948, 2023). "Previous studies have identified EZH2 and TOP2A as comarkers of cancer progression." (PMID 38008711, 2023). "Recent research has demonstrated that EZH2 also performs canonical as well as potentially opposing non-canonical roles in multiple types of cancer, and our results indicate that this is also true in the context of myeloid differentiation." (PMID 37035245, 2023). "Specifically, disrupting PRC2 allosteric activation can override the hyperactivity of EZH2Y641X and inhibit the proliferation of PRC2/EZH2-addicted tumors, providing a potential therapeutic strategy for PRC2/EZH2-addicted cancers by targeting EZH2SRM–EZH2SET-I and EZH2SRM–EED interactions." (PMID 37051671, 2023).
cancer (continued). "Given the important role that EZH2 plays in controlling H3K27me3-induced cell growth and cancer development, it is not surprising that such a tightly regulated mechanism has evolved to control the oncogenic function of EZH2." (PMID 37069142, 2023). "A notable example is the relationship between PRC2/EZH2 and the SWI/SNF complex in cancer." (PMID 37664059, 2023). "Thus, current work provides new insights into understanding the potential roles of EZH2-mediated SPOCK2 or SPRED1 in LUAD and their potential as biomarkers for cancer therapy and prognosis." (PMID 36629984, 2023). "EZH2 may accelerate cancer metastasis by directly participating in EMT, and therefore, in this study we further examined the role of TRIP12-EZH2 signaling axis in regulating EMT." (PMID 38031139, 2023). "In summary, our study has revealed a key pathway underlying NE gene upregulation by ADT, as well as established novel relationships between CREB1 and REST, and between EZH2 and REST, which may also have implications in other cancer types and in neurobiology." (PMID 37886478, 2023). "Since there is no pan-cancer study on EZH2, research on this topic is of great importance to deepen the understanding of cancer development and develop a novel therapeutic target for improving patient prognosis." (PMID 36545914, 2023). "We then explored by real-time qPCR the impact of miR-662 overexpression in MDA-MB-231 cells on expression levels of well-established stemness markers that are involved in embryogenesis and cancer –NOTCH1, WNT7b, ZEB1, TCF3, CTNNB1, CD44, CD24, SNAI2, OCT-04, c-MYC, EZH2–." (PMID 37443350, 2023). "EZH2 has been shown to increase the expression of circRNA_0082835, an hsa-miR-429 sponge in cancer cells, creating another negative feedback loop-based regulation between EZH2 and hsa-miR-429." (PMID 37296866, 2023). "Interestingly, about 50% of PCaT samples and derived organoids expressed another cancer marker, TMPRSS2-ERG, in addition to AMACR and EZH2." (PMID 36769153, 2023). "PCaT samples and derived PDOs expressed cancer markers AMACR, EZH2 and TMPRSS2-ERG." (PMID 36769153, 2023). "As the core component of PRC2, EZH2 has been proven to have carcinogenic effects in cancer, but current EZH2 inhibitors are not effective in inhibiting the oncogenic activity of EZH2; thus, EZH2-based PROTACs were designed to degrade PRC2 complexes." (PMID 36770884, 2023). "Recently, increasing number of studies uncovered the crucial role of nonenzymatic activity of EZH2 in different cancers progression." (PMID 36642705, 2023). "Aberrant KRAS activity renders LUAD cancer cell lines vulnerable to MTHFD2 and EZH2 inhibitors." (PMID 37069494, 2023). "Accumulating evidence suggests that EZH2 functions as a transcriptional factor or coactivator in cancer, independent of PRC2, promoting oncogenesis through multiple pathways." (PMID 37175580, 2023). "This strongly suggests that non-enzymatic functions of EZH2 are not only relevant in cancer progression, but also to therapeutic approaches." (PMID 37664059, 2023). "It has been reported that DZNep globally inhibits histone methylation in cancer cells and is not selective for EZH2." (PMID 37476157, 2023). "Early PCCs and PDOs derived from the tissues of PCa patients expressed prostate basal and luminal epithelial markers, as well as cancer markers AMACR, TMPRSS2-ERG, and EZH2, the latter being a promising candidate to mark the transition from the indolent to aggressive PCa." (PMID 36769153, 2023). "We further analyzed the correlation between EZH2 and TOP2A expression in cancer." (PMID 38008711, 2023). "For example, the HMT enzyme, enhancer of zeste homolog (EZH2), the catalytic subunit of polycomb repressive complex 2 (PRC2), responsible for the trimethylation of histone H3 at lysine 27 (H3K27Me3), has been reported to be upregulated in cancer." (PMID 37627320, 2023).
cancer (continued). "Besides, several methyltransferases like SMYD3, EZH2, and SETDB1 are also abnormally expressed in common human cancer lines." (PMID 37220590, 2023). "However, in several highly malignant and lethal cancers including ENKTL, the oncogenic role of EZH2 is frequently H3K27 tri-methylation independent." (PMID 38031139, 2023). "Again, to provide preliminary indications of the clinical relevance of our identified mechanism of metabolic regulation in cancer involving PROX1, SIRT3, and EZH2, we examined the correlations between these protein expression levels in CRC patient tissues and clinical parameters and prognosis." (PMID 36594098, 2023). "EZH2 (Enhancer of Zeste Homolog 2), a core subunit of PRC2 (polycomb repressive complex 2), has been reported as a key epigenetic regulator of histone methylation involved in cancer progression." (PMID 37171386, 2023). "However, in several other cancer types like ENKTL, EZH2-mediated oncogenesis is enzymatically- and PRC2-independent, and naturally, inhibitors aiming at enzymatic disruption are ineffective to target oncogenic EZH2." (PMID 38031139, 2023). "However, EZH2-induced silencing of PHACTR2-AS1 promoted ribosome synthesis and ribosomal DNA (rDNA) instability that, in turn, supported cancer cell proliferation and metastasis." (PMID 37275549, 2023). "The carcinomas with BAP1 or MTAP loss included one adenocarcinoma with <80% EZH2 staining and negative CD117 staining, such that the addition of BAP1 and MTAP to a panel of EZH2 (≥80% threshold) and CD117 slightly increased the sensitivity for carcinoma from 92% to 95%." (PMID 37190202, 2023). "MEG3 physically interacts with the EZH2 subunit of the PRC2 complex to repress the expression of several genes involved in TFG-β signaling (e.g., SMAD2 or TGFBR1), increasing the aggressiveness of cancer by promoting invasion and metastasis." (PMID 35054945, 2022). "Importantly, EZH2-mediated SMAD3 methylation not only rendered cancer cells more vulnerable to TGFB1 and promoted cancer cell EMT and metastasis, but also showed a positive correlation with poor patient survival." (PMID 35085106, 2022). "Given that EZH2-mediated SMAD3 K53/K333 methylation is necessary for TGFB/SMAD signaling pathway activation and cancer metastasis, we investigated whether SMAD3 methylation could be therapeutically targeted." (PMID 35085106, 2022). "Downregulation of EZH2, AR, and PSA expression in all tested PCa cells by the Myc inhibitor 10058-F4 suggests that HSP60 may regulate these cancer-promoting proteins via c-Myc." (PMID 35653190, 2022). "EZH2 expression revealed a positive relationship with infiltrating levels of CD8 + T cells in 20 cancer cases, those of macrophages for 12 cancers, those of CD4 + T cells for 18 cancers, those of DCs for 19 cancers, and those of neutrophils for 24 cancers." (PMID 35659256, 2022). "Enhancer of Zeste Homolog 2 (EZH2) and Euchromatic Histone Lysine Methyltransferase 2 (EHMT2) both maintain repressive H3K27 and H3K9 methylation histone marks, respectively, and are frequently overexpressed in cancer." (PMID 35326684, 2022). "EZH2 inhibitors have been just shifting from the bench to the bedside, but the combination scheme in cancer therapy has not been fully explored yet." (PMID 36263120, 2022). "EZH2 expression revealed a positive relationship with the degree of CD8 + T cell infiltration in 20 cancers, macrophages in 12 cancers, CD4 + T cells in 18 cancers, DCs in 19 cancers, and neutrophils in 24 cancers." (PMID 35659256, 2022). "The multifarious functional involvement of EZH2 in physiological and pathological conditions including cancer is potentiated by the existence of both canonical- and non-canonical EZH2 activities." (PMID 35884510, 2022).
cancer (continued). "It was showed that EZH2 stimulates EMT and leads to an increase in cancer metastasis." (PMID 35236381, 2022). "Combination of the BIRC5 inhibitor YM155 and EZH2 inhibitors achieved remarkable synergistic effect in cancer cell killing and this is independent of the canonical functions of EZH2 in methylating H3K27." (PMID 36612203, 2022). "Interpreting the mechanism of EZH2 and DNMT1 conductor in cancer immunity throws light on the promising benefit of the combinational treatment of epigenetic-modifying drugs (such as EZH2 or DNMT1 inhibitor) and immunotherapy (such as TAMs modulator) in patients with cancer." (PMID 36038549, 2022). "Despite extensive studies, the functions of PRC2, especially with regard to EZH2 in cancer, are not entirely clear." (PMID 36612203, 2022). "Interestingly, HMGA1P6 and HMGA1P7 also regulate the expression of EZH2, HMGA2, and other cancer-related genes with a critical role in cancer progression by sponging miRNAs able to target these genes." (PMID 35804851, 2022). "Furthermore, a marked decrease in HMT activity and a decrease in EZH2 protein expression and H3K27 trimethylation were noted in histones isolated from luteolin-treated cancer cells." (PMID 35327559, 2022). "Promising advances for this class of cancer therapeutics disrupt the complex formation of PRC2 rather than EZH2 enzymatic activity." (PMID 35795673, 2022). "Besides EZH2, overexpression of other PcG proteins such as SUZ12 and BMI1 have also been shown to favor cancer progression." (PMID 35563864, 2022). "We also sequenced the polycomb complex repressor 2 (PRC2) components EZH2, SUZ12, and EED, as frequently co-altered with RAS pathway genes in other cancers in 104 samples from our cohort, and found that 50% and 13.8% of RAS+ and RAS− cases, respectively had concomitant PRC2 alteration (p < 0.0001)." (PMID 35354920, 2022). "The first targeted degrader of EZH2 showed promising results as it was demonstrated to be efficient in the degradation of EZH2 in different cancer cell lines, including the non-malignant PCa cell line PNT2." (PMID 36135315, 2022). "These experiments highlight the fact that ncRNAs regulate EZH2 expression and can be considered as reliable and non-invasive biomarkers for cancer prognosis and diagnosis." (PMID 35236381, 2022). "Considering their crucial role in the epigenetic regulation of cancer processes, selective inhibition of the histone methyltransferases NSD1, SETD2 and EZH2 could offer beneficial therapeutic strategies in treating cancer." (PMID 36230787, 2022). "Although it is well established that EZH2 is a key component of the PRC2 complex that silences gene expression by methylating H3K27, its role targeting non-histone substrates has been shown to be important in some cancers." (PMID 36612203, 2022). "MEG3 promotes EZH2 ubiquitination, leading to upregulation of LATS2, a tumor suppressor kinase that inhibits cell proliferation and metastasis through the Hippo signaling pathway in several types of cancer." (PMID 35054945, 2022). "Tazemetostat, although clinically approved for and potent in selected cancer entities predominantly characterized by canonical EZH2 activities, specifically blocks EZH2 histone methyltransferase activity, but does not interfere with EZH2 expression." (PMID 35884510, 2022). "It is also reported EZH2 could interact with RNAs to exert its functions dependent or independent on PRC2, especially in cancers." (PMID 36578923, 2022). "However, only one methylase, EZH2 (KMT6A), and one demethylase, LSD1 (KDM1), are currently under extensive evaluation in the clinic for cancer therapy using inhibitors which target the enzyme activity." (PMID 35406676, 2022). "Furthermore, a marked decrease in HMT activity and a decrease in EZH2 protein expression and H3K27 trimethylation were noted in histones isolated from cancer cells treated with apigenin." (PMID 35327559, 2022). "It was reported that miRNA/EZH2 axis affects EMT and metastasis of cancer cells." (PMID 35236381, 2022).